KRAS (KRas proto-oncogene, GTPase)
Diseases named in the same sentence as KRAS in open-access papers (continued):
Sharing a sentence is not in itself a finding about the gene and the disease.
lung adenocarcinoma (continued). "Sequencing of the 41 lung adenocarcinomas showed that 14 tumours had KRAS mutations, and that 7 tumours had EGFR mutations." (PMID 27456471, 2016). "Consistently with these observations, we found that a moderate up‐regulation of OTUB1 is significantly associated with poorer overall survival in TCGA lung adenocarcinoma patients with wt KRAS compared to low‐expressing OTUB1." (PMID 26881969, 2016). "The result indicated that KRAS mutation occurs more frequently in lung adenocarcinoma (RR=1.16 p=0.016), and in former or current smokers (RR=1.13 p=0.017), but not in male gender (RR=1.07 p=0.142)." (PMID 26840022, 2016). "As the most common oncogenic event in lung adenocarcinoma, KRAS mutations represent the primary therapeutic target for drug development." (PMID 27626312, 2016). "It seemed that KRAS mutation occurs more frequently in lung adenocarcinomas (approximately 30%), in the Caucasian population, and in the population with smoking history." (PMID 26840022, 2016). "KRAS mutations occur in approximately 30 % of lung adenocarcinomas in Caucasians and in approximately 10 % of lung adenocarcinomas in Asians." (PMID 27655296, 2016). "We observed that while BUB1B knockdown reduced anchorage-independent growth of all human lung adenocarcinoma and colon cancer cell lines that we tested, those harboring KRAS mutations were slightly more sensitive." (PMID 26000094, 2015). "We previously reported that patients with lung adenocarcinomas with KRAS gene mutations and strong proliferating activity had poorer outcomes, even in the early stage of the disease." (PMID 26544866, 2015). "KRAS is the most frequently mutated oncogene in patients with lung adenocarcinoma, and many studies have been conducted to evaluate its clinical and therapeutic implications." (PMID 26471290, 2015). "The driver genes involved in lung adenocarcinoma include KRAS, EGFR, ALK, and BRAF, and those implicated in lung squamous cell carcinoma (LSCC) include PIK3CA, FGFR1, EGFR, PDGFRA, and DDR2." (PMID 26373952, 2015). "In contrast, KRAS mutations were detected in 35–50% of lung adenocarcinomas in Caucasian patients but in less than 5% of lung adenocarcinomas in Chinese patients." (PMID 26134262, 2015). "Six lung adenocarcinoma cell lines, with KRAS, EGFR, or ALK driver mutations were evaluated for Debio 1143 dose-dependent growth inhibition to identify optimal concentrations for use in combination assays." (PMID 26485762, 2015). "Lung adenocarcinoma possesses distinct patterns of EGFR/KRAS mutations between East Asian and Western, male and female patients." (PMID 26160836, 2015). "KRAS mutations are detected in approximately 20%–25% of lung adenocarcinoma and 4% of lung squamous cell carcinoma." (PMID 26018876, 2015). "In summary, the results of the present study suggested that the up-regulation of S100A11 played a role in tumor progression, particularly in KRAS-mutated lung adenocarcinomas." (PMID 26544866, 2015). "Recent genomic studies in lung adenocarcinoma have identified other potential therapeutic targets, such as mutations in KRAS, HER2 and BRAF, ROS1 rearrangements, RET fusions and MET amplification." (PMID 25789627, 2015). "Multiplex ddPCR assays thus provide a highly efficient methodology to identify KRAS mutations in lung adenocarcinoma." (PMID 26413866, 2015). "This gene incurred frequent silent mutations in lung adenocarcinoma (indicated by a yellow dot) that overlapped with mutations in KRAS, much as anticipated." (PMID 26047463, 2015). "Collectively, these mouse model studies clearly show a prooncogenic role for NOTCH1 in lung adenocarcinoma development within a KRAS-mutated cellular context." (PMID 26491213, 2015).
lung adenocarcinoma (continued). "We determined that lung adenocarcinoma cells harboring diverse oncogenic mutations such as KRAS and EGFR were sensitized to ionizing radiation." (PMID 26010604, 2015). "It was demonstrated that loss of CDK4 activity was synthetically lethal with KRAS mutation in lung adenocarcinoma." (PMID 26410619, 2015). "Mutations in the RAS protein subfamily (HRAS, NRAS, KRAS) occur frequently in various types of cancer and have a relatively high frequency in lung adenocarcinomas." (PMID 26170901, 2015). "Since the results obtained suggested that the up-regulation of S100A11 was involved in tumor progression, particularly in KRAS-mutated lung adenocarcinomas, its prognostic value was subsequently verified." (PMID 26544866, 2015). "In lung adenocarcinomas, KRAS mutation is found in about one third of the tumours in Caucasian populations, as opposed to less than one tenth is Asian populations." (PMID 24739673, 2014). "The main goal of this study was to report the frequency and spectrum of KRAS mutations in unselected group of Moroccan lung adenocarcinoma patients." (PMID 24729895, 2014). "The data here suggest that in addition to being mutated in cancers, KRAS is also amplified in ovarian, gastric, lung adenocarcinoma, and uterine cancers, with a copy number range 10–40 in ovarian cancers." (PMID 24874471, 2014). "The novel procedure was used for analyzing patterns of copy-number alterations in lung adenocarcinomas, with respect to Kirsten Rat Sarcoma Viral Oncogene Homolog gene (KRAS) mutation status, while controlling for a cohort effect." (PMID 24739673, 2014). "KRAS mutations are present in approximately 30% of lung adenocarcinomas and less commonly in squamous NSCLC (~5%)." (PMID 25157335, 2014). "The proposed procedure is used to decipher heterogeneity of lung adenocarcinomas, with respect to KRAS mutation, based on copy-number alterations." (PMID 24739673, 2014). "When investigating patterns of copy-number alterations in lung adenocarcinomas, with respect to KRAS mutation status and after adjustment for a cohort effect, our proposed strategy highlights two subgroups of pure or nearly pure wild-type KRAS tumors." (PMID 24739673, 2014). "The proximal-proliferative subtype in lung adenocarcinoma is characterized by an enrichment of mutations in KRAS along with inactivation mutations in STK11." (PMID 25405470, 2014). "The aim of the clinical study that prompted this methodological work was to decipher heterogeneity of lung adenocarcinomas with respect to KRAS mutation status based upon whole-genome copy-number alterations." (PMID 24739673, 2014). "The objective of this study was to report the frequency and spectrum of KRAS mutations in a group of Moroccan lung adenocarcinoma patients." (PMID 24729895, 2014). "iMDK inhibited the PI3K/AKT pathway and suppressed KRAS-mutated lung adenocarcinoma by inducing apoptosis in vitro and in vivo." (PMID 23976985, 2013). "EGFR mutations were detected in 10% (7/71) and KRAS mutations were detected in 35% (19/54) of the lung adenocarcinoma cases." (PMID 23817662, 2013). "We used an earlier version of our eSNV workflow to call KRAS mutations in lung adenocarcinoma samples with 100% accuracy." (PMID 24223926, 2013). "Several other driver molecular alterations have been identified in lung adenocarcinoma, including somatic mutations of KRAS, BRAF, STK11, DDR2 and members of the FGFR family, as well as ALK rearrangements." (PMID 24236184, 2013). "Clearly, further molecular stratification within the EGFR and KRAS mutation-defined lung adenocarcinoma groups has the potential to reveal new targets for synergistic treatment and provide insights into resistance mechanisms." (PMID 24205279, 2013). "There were no significant gender differences in age, pathological nodal status, lymphatic permeation, blood vessel invasion or mutation spectra for either EGFR- or KRAS-mutated lung adenocarcinomas." (PMID 24179496, 2013).
lung adenocarcinoma (continued). "To determine if DOK2 genomic loss was a feature of a specific genomic class of lung adenocarcinoma, we analyzed the relationship of DOK2 loss with mutation of EGFR or KRAS in 199 primary human lung adenocarcinomas." (PMID 24255704, 2013). "EGFR and KRAS mutations were detected in 233 (45%) and 56 (11%) of the total 521 lung adenocarcinoma patients, respectively." (PMID 24179496, 2013). "The study in which KRAS mutations were analyzed in nearly 500 lung adenocarcinomas showed that KRAS mutations were found in 15%, 22% and 25% of tumors from never smokers, former smokers and current smokers respectively." (PMID 27234388, 2013). "iMDK inhibited the growth of MDK-expressing H441 lung adenocarcinoma cells that harbor an oncogenic KRAS mutation and H520 squamous cell lung cancer cells in vitro." (PMID 23976985, 2013). "KRAS-mutated lung adenocarcinomas are more predominant in Caucasians (~30%) than East Asians (~10%)." (PMID 24179496, 2013). "EGFR and KRAS mutations are the two most frequent oncogenic events in human lung adenocarcinoma, occurring in approximately 15% and 30% of U.S. lung adenocarcinoma cases, respectively." (PMID 24255704, 2013). "This was clearly the case in a few of our specimens, including both colorectal and lung adenocarcinomas, where quantitative ASLNAqPCR results of KRAS and BRAF analysis showed that mutations were present in a minority of the tumor cells." (PMID 22558339, 2012). "KRAS mutations are reported in 15–25% of patients with lung adenocarcinoma and are typically mutually exclusive with EGFR mutations or ALK gene rearrangements." (PMID 25562798, 2012). "The overall frequency of EGFR mutations in lung adenocarcinomas in this West European population is within the frequency range of North American and South European populations, whereas KRAS mutation frequency is higher than in any population described to date." (PMID 22528563, 2012). "A different KRAS mutation type between primary lung adenocarcinomas and corresponding lymph node metastases was also observed in only 1% of the patients." (PMID 21364579, 2011). "Of 237 lung adenocarcinoma tumors, the small number with both KRAS mutation and CNG were associated with shortened survival." (PMID 19826477, 2009). "The association between KRAS alterations and clinical and other genetic factors in 288 lung adenocarcinomas." (PMID 19826477, 2009). "Recent studies have indicated that EGFR mutations are mutually exclusive with KRAS mutations in lung adenocarcinomas." (PMID 18485879, 2008). "Another rapid autopsy study was carried out on a KRAS G12C-mutated lung adenocarcinoma patient who developed rapid resistance after initial response to AMG510, with the observation of downregulated G2/M checkpoint regulators and E2F target genes, among other overlapping resistance mechanisms." (PMID 41541668, 2026). "The EGFR and KRAS genes are mutation hotspots in lung adenocarcinoma that occur randomly in MPLC." (PMID 41556052, 2026). "Additionally, STK11/LKB1 mutations cause resistance to PD-1 blockade in KRAS-mutated lung adenocarcinoma.The reduced antigen-presenting ability of tumor cells is characterized by abnormalities in MHC molecules." (PMID 41293265, 2025). "For example, in the context of the KRAS G12D mutation, deletion of chromobox 4 destabilizes chromosomes and activates multiple signaling pathways, including the Hippo pathway, which are essential for lung adenocarcinoma progression." (PMID 40042761, 2025). "KRAS mutations in lung adenocarcinoma are more frequent in Caucasians than in Asians." (PMID 38710944, 2025). "KRAS mutations are responsible for a quarter of all lung adenocarcinomas." (PMID 41219537, 2025). "Therefore, the expression of HNF4α has potential as a therapeutic target in lung adenocarcinomas, particularly KRAS-mutated lung adenocarcinomas." (PMID 38710944, 2025).
lung adenocarcinoma (continued). "Among all KRAS mutations in NSCLC, the most prevalent is the single-nucleotide variant p.G12C, which results in a glycine-to-cysteine substitution at codon 12 in exon 2 and accounts for approximately 40% of KRAS mutations, with an overall prevalence of about 13% in lung adenocarcinoma." (PMID 41155693, 2025). "Recent studies have shown that the FOSL1 may be a potential prognostic marker and target for human lung adenocarcinoma with KRAS mutations." (PMID 40761262, 2025). "Lung adenocarcinoma, for instance, could be further classified based on driving mutations in KRAS and/or EGFR genes." (PMID 41269529, 2025). "Notably, EGFR and KRAS mutations, which are common in lung adenocarcinoma, activate key signaling cascades such as MAPK/ERK and PI3K/AKT, which in turn modulate the expression of several oncogenic lncRNAs." (PMID 40650307, 2025). "Conversely, KRAS mutations occur in only about 30% of lung adenocarcinomas." (PMID 40656425, 2025). "KRAS activating mutations represent the most prevalent oncogenic drivers in lung adenocarcinoma, occurring in approximately 25% to 32% of cases across both early and advanced stages of the disease, whereas these mutations are detected in less than 1% of squamous cell carcinoma cases." (PMID 41155693, 2025). "No consistent associations between TAP1 or TAP2 downregulation and age, gender, disease stage or smoking status were identified, and the frequency of cancer cell TAP1 and/or TAP2 downregulation was comparable across lung adenocarcinomas harboring activating mutations in EGFR or KRAS." (PMID 40091029, 2025). "In this Lung-iKRAS (L-iKRAS) model, first described by the Varmus laboratory, expression of oncogenic KRAS in club cells, in combination with loss-of-function mutations in tumor suppressor genes, efficiently drives formation of lung adenocarcinoma in both male and female mice." (PMID 39782689, 2025). "However, KRAS, which is mutated in 30% of lung adenocarcinomas, has long been defined as ‘undruggable’." (PMID 41002380, 2025). "Furthermore, KRAS G12C mutations are prevalent in lung adenocarcinoma, comprising a significant proportion of cases." (PMID 38802900, 2024). "Lung adenocarcinomas in Black or Asian patients tend to exhibit KRAS mutations other than G12C more frequently than White patients, who are more likely to have tumors driven by the clinically targetable KRAS G12C." (PMID 38668053, 2024). "AT2 cells are the likely cells of origin of lung adenocarcinomas harboring KRAS mutations." (PMID 38617360, 2024). "Among them, KRAS gene mutations are found in ~30% of lung adenocarcinomas (LUAD)." (PMID 38734764, 2024). "Interestingly, ZC3H11A overexpression correlates with the occurrence of KRAS mutations in lung adenocarcinoma, providing a link between the Ras/MAPK pathway and ZC3H11A." (PMID 38342435, 2024). "KRAS mutations are the most common oncogenic mutations in lung adenocarcinoma in Black Americans." (PMID 39436906, 2024). "Additionally, even though KRAS-G12C mutations are the most frequent in lung adenocarcinoma, there is a small percentage of tumors with this specific mutation in other tumor types as well." (PMID 38278976, 2024).
lung adenocarcinoma (continued). "Mutations in the oncogene KRAS drive tumorigenesis in 30% of lung adenocarcinoma cases." (PMID 38635884, 2024). "At this concept, a study evaluated KRAS mutations in minor clones in patients with lung adenocarcinoma treated with EGFR-TKI, concluding that KRAS mutations might hinder the effectiveness of anti-EGFR therapy." (PMID 38793038, 2024). "Additionally, an association between the KRAS p.Gly12Cys variant and lung adenocarcinoma in smokers has been documented." (PMID 39001385, 2024). "It is worth noting that the data presented on the A549 non-small cell lung cancer cell line correspond to a lung adenocarcinoma cell line, which specifically carries KRAS and CDKN2A gene mutation, with KRAS being one of the most commonly observed mutations in LC." (PMID 38674017, 2024). "Additionally, in another study, researchers suggested that KRAS mutation was an independent predictor of worse overall survival in patients with lung adenocarcinoma treated with first line pembrolizumab monotherapy." (PMID 38793038, 2024). "Gene mutations observed differ between lung adenocarcinoma and lung squamous cell carcinoma, with KRAS, EGFR, LPHN3, KEAP1, and TLR4 being relatively common in lung adenocarcinoma, whereas BAI3, FBXW7, GRM8, ERBB4, MUC16, and RUNX1T1 are common in lung squamous cell carcinoma." (PMID 39594843, 2024). "However, another subtype of KRAS mutation (KRAS G12D) was found to be associated with a lower mutation burden in lung adenocarcinoma, resulting in a suppressed immune response." (PMID 38481800, 2024). "Beyond COVID‐19, reduced ADAM17 expression in lung may have promising implications in KRAS mutation‐driven lung adenocarcinoma." (PMID 38886986, 2024). "The results of this study may provide some information for the plan of neoadjuvant therapy and the design of clinical trials for lung adenocarcinoma patients with KRAS G12C mutation." (PMID 37284902, 2023). "The most common KRAS mutation is KRAS-G12C which is present in about 13% of lung adenocarcinomas." (PMID 37675274, 2023). "LZTR1 deficiency increased RIT1 and KRAS expression in lung adenocarcinoma cells." (PMID 37626065, 2023). "The mutation frequencies of a consecutive population-based Swedish cohort have been proven to be similar to those observed in other Western populations, except for a notable high frequency (43%) of activating KRAS mutations among patients with lung adenocarcinoma." (PMID 37345046, 2023). "Among these, KRAS mutations are the most common oncogenic aberrations found in almost 25%–30% of lung adenocarcinoma cases, and were the first genetic lesions identified in lung adenocarcinoma more than 30 years ago." (PMID 37882674, 2023). "After DEN exposure, A/J mice developed lung adenocarcinoma, 82% of which possessed KRAS mutations." (PMID 36969176, 2023). "Since proteosome ubiquitination and degradation are essential steps in response to HSP90 inhibition, this alteration could be the result of a differential reaction in the KRAS-mutated and TN groups compared to the other lung adenocarcinoma molecular subgroups." (PMID 37762133, 2023). "Here, we demonstrated that the loss of LZTR1 could induce the accumulation of RIT1 and KRAS in lung adenocarcinoma cells and promote tumor growth and metastasis." (PMID 37626065, 2023). "Histopathological analysis revealed bone metastasis of a KRAS G13D-mutated lung adenocarcinoma." (PMID 37718451, 2023). "Moreover, a significant upregulation of ZC3 has been observed in KRAS-mutant lung adenocarcinomas, where KRAS mutations are frequently observed molecular alterations in non-small cell lung cancers and serve as a predictor of poor prognosis." (PMID 38033582, 2023).